ACHE (acetylcholinesterase (Yt blood group))
Diseases named in the same sentence as ACHE in open-access papers (continued):
Sharing a sentence is not in itself a finding about the gene and the disease.
Cognitive impairment (continued). "Hence, our study highlighted that the neuroprotective activity of PIRA against DOX-induced cognitive deficits can be linked to reductions of AChE levels, neuro-inflammatory mediators, pro-apoptotic proteins, and oxidative stress." (PMID 36559014, 2022). "In addition, coumarins exhibit acetylcholinesterase (AChE) inhibitory activity, which in turn increases acetylcholine (ACh) levels in the brain, ultimately leading to decreases in cognitive impairment caused by Aβ1–42 injection." (PMID 35439990, 2022). "Similarly, in vivo studies showed that Lycopodium selago extract, administered to zebrafish (Danio rerio) with cognitive impairment caused by scopolamine, alleviates cognitive deficits, inter alia, by regulating ACHE activity." (PMID 35893381, 2022). "Importantly, the confirmed miRNA 132/212 target Acetylcholinesterase (AChE) has been independently implicated in cognitive deficits in the aftermath of ischemic stroke." (PMID 34359879, 2021). "Moreover, the cholinergic activity enhancement exerted by E100 in BTBR mice and the accompanied possible influence on cognitive impairment linked with sociability deficits was correlated to AChE activity evaluation in the cerebral tissues." (PMID 32872194, 2020). "AChE is a neurotransmitter that is closely associated with the function of learning and memory, and an increase in AChE content can damage the cholinergic nerve, causing a cognitive impairment, which means AChE can be used as an indicator for revaluating the learning and memory." (PMID 29736181, 2018). "AChE is another factor associated with cognitive disorders and with Aβ accumulation." (PMID 29137190, 2017). "Therefore, high-fat diet-induced oxidative stress caused cognitive defects according to the increase of AChE activity." (PMID 26161118, 2015). "One of the principal therapeutic strategies for managing Alzheimer’s disease involves the use of acetylcholinesterase (AChE) inhibitors, which aim to prevent the breakdown of acetylcholine, thereby enhancing cholinergic transmission and alleviating symptoms associated with cognitive impairment." (PMID 40243991, 2025). "However, excessive AChE activity results in constant ACh deficiency and cognitive deficits." (PMID 29740317, 2018). "On the meanwhile, it was reported that the activity of acetylcholinesterase (AChE, a neurotransmitter associated with learning and memory) was increased in serum and cerebral cortex of diabetic rats, which may contribute to cognitive deficits exhibited in diabetes." (PMID 24386004, 2013). "In the present study, we observed elevated AChE level in AlCl3 induced group compared to control group after 45 days and this is also correlated with cognitive deficit." (PMID 41502474, 2026). "In cognitive impairment and change in behaviour, the activity of AChE has been reported either increasing or decreasing." (PMID 41502474, 2026). "Previous research findings documented the inhibition of AChE activity for the management of cognitive impairment and neurobehavioral deficit." (PMID 40318207, 2025). "This action leads to increased acetylcholinesterase (AChE) activity and reduces cholinergic neurotransmission, resulting in cognitive deficits that resemble the pathological features of AD." (PMID 41178976, 2025). "Treatment with rosiridin dose-dependently reduced AChE activity, suggesting neuroprotective effects by preserving the cholinergic function and potentially alleviating cognitive deficits." (PMID 39949093, 2025). "In this study, significantly reduced AChE activity observed in the cuprizone (CPZ)-treated group at week 5 is indicative of impaired cholinergic neurotransmission, likely contributing to cognitive deficits commonly associated with CPZ-induced demyelination." (PMID 41155593, 2025). "This aligns with evidence that naringenin mitigates Aβ-induced cognitive impairment by AChE activity." (PMID 40486726, 2025).
Cognitive impairment (continued). "Elevated AChE activity leads to reduced acetylcholine levels, contributing to the cognitive deficits characteristic of AD." (PMID 40283926, 2025). "The results indicate a relation between neuro-inflammation and cognitive impairment, highlighting its contribution to the dysregulation or increase in AChE activity, which in turn results in behavioral changes in rats exhibiting dementia." (PMID 40325262, 2025). "AChE, responsible for the breakdown of ACh, is typically elevated in AD patients, especially in the cortex and hippocampus, contributing to cognitive impairment." (PMID 40002547, 2025). "The H40-9 (136.49 ± 18.30%, p < 0.01), and MC (108.79 ± 25.81%, p < 0.05) groups showed significantly lower AChE activities than the PC group, indicating cognitive impairment." (PMID 40427447, 2025). "Huperzine A (HupA), derived from Huperzia serrata, inhibits AChE, increasing acetylcholine levels in the synaptic cleft, thereby improving neurotransmission and alleviating cognitive deficits in AD." (PMID 40153574, 2025). "Mechanistically, miR-132-5p facilitates cognitive impairment by diminishing acetylcholinesterase (AChE) expression, whereas miR-137-5p intensifies Aβ-induced neurotoxicity." (PMID 41154171, 2025). "Inhalation of EOCO significantly reduced AChE activity in rats injected with Aβ-induced cognitive impairment (p < 0.05)." (PMID 40002547, 2025). "Alkaloids reversibly inhibit AChE and improve cholinergic neurotransmission, similar to most Annonaceae alkaloids, which act on cognitive disorders." (PMID 39765648, 2024). "AChE, a serine hydrolase that plays a crucial role in cholinergic neurotransmission, is a key target in the treatment of cognitive impairments due to its function in acetylcholine hydrolysis." (PMID 39796512, 2024). "Oxidative stress can impair cholinergic neurons, further increasing AChE activity and aggravating cognitive deficits." (PMID 39911825, 2024). "Since the introduction of the first AChE inhibitors in 1997, these compounds have become the primary class of drugs used as the first-line pharmacotherapy for addressing cognitive impairments in patients with AD." (PMID 39796512, 2024). "CGA inhibits acetylcholinesterase (AChE) activity in rat brains, suggesting its beneficial effect against cognitive impairment." (PMID 38612964, 2024). "AChE hydrolyzes acetylcholine, which is important for learning and memory, so its rapid degradation by AChE leads to dementia and Cognitive Impairment (CI)." (PMID 39050734, 2024). "Studies with histamine H3 receptor (H3R) blockers and acetylcholinesterase (AchE) blockers are considered potential therapeutic agents for the management of various cognitive impairments." (PMID 39316620, 2024). "Myricetin treatment resulted in the suppression of Fe2+-induced cell death in SH-SY5Y cells and showed anti-AChE activity and reversed Scopolamine-induced cognitive deficits in a mouse model." (PMID 36986610, 2023). "In the current study, we evaluated the anti-AChE potential of GCEO in the SCOP-induced model of cognitive impairment." (PMID 36840131, 2023). "Huperzia serrata is an interesting medicinal plant used in traditional medication in Asia for treating cognitive impairment, dementia, and schizophrenia, and one of its compounds, huperzine A, is a well-established competitive reversible inhibitor of AChE." (PMID 36986610, 2023). "An increase in AChE activities is reported in the present research in the negative control group (SG mice), as a biomarker of scopolamine- induced cognitive impairment." (PMID 38004485, 2023). "Although sarin-induced changes in AChE were similar to those documented in the literature, AChE inhibition alone was unable to account for the prolonged cognitive impairment." (PMID 37106826, 2023). "Animals exhibited augmented neuroinflammation, oxidative stress, enhanced AChE activity, and cognitive deficits over time post-ICV-STZ administration." (PMID 37443762, 2023).
Cognitive impairment (continued). "Since the main cognitive deficits are attributed to cholinergic connections, the drugs that are used in this field are based on the inhibition of AChE." (PMID 36829840, 2023). "Cholinergic neurodegeneration is considered a critical pathological change that correlates with cognitive impairment in AD, and drugs inhibiting AChE activity currently represent the most available clinical symptomatic treatment for AD patients." (PMID 36056992, 2023). "Our study proposes the examination of CP, SCOP, and CP + SCOP as potential AChE inhibitors for their ability to modulate cognitive deficits." (PMID 35212831, 2022). "To further investigate the mechanism of MO in both MOE and MOO, we analyzed the AChE activity which represented cholinergic status in mild cognitive impairment." (PMID 35299766, 2022). "Intracerebroventricular injection of nootkatone (0.02 mg/kg and 0.2 mg/kg) ameliorates Aβ1–42-induced cognitive impairment by upregulating antioxidant and anti-ACHE activities in the hippocampus." (PMID 36533181, 2022). "The bark of Eucommia ulmoides decreased AChE activity in the hippocampal and cortex of scopolamine-induced learning and cognitive impairment mice." (PMID 35607702, 2022). "The FDA-approved drugs for AD ameliorated cognitive impairment by inhibiting the breakdown of ACh by both AChE and BuChE." (PMID 36422287, 2022). "We studied the anti-AChE activity of Convolvulus pluricaulis (CP) in a zebrafish model of cognitive impairment induced by scopolamine (SCOP)." (PMID 35212831, 2022). "Aqueous CP extract has shown significant AChE inhibition in the cortex and hippocampus of male Wistar rats with scopolamine-induced cognitive impairment." (PMID 35212831, 2022). "For example, a combination of memantine and AChE inhibitors, in particular galantamine, show a significant effect in cognitive impairment because of their complementary pharmacological effects." (PMID 35203924, 2022). "This indicates that inhibition of AChE activity must be one mechanism by which EA twig extracts improve cognitive impairments." (PMID 36615789, 2022). "In a scopolamine-induced cognitive impairment mouse model of AD, the oral administration of AO for 30 days increased the levels of ACh and M1 receptors and decreased the activity of ACHE." (PMID 36533181, 2022). "Beta-carotene was found to inhibit AChE in murine models of Alzheimer’s disease, indicating its ability to potentially attenuate cognitive deficits via its antioxidant effects and inhibition of acetylcholinesterase." (PMID 36013492, 2022). "AChE levels in the rats’ brains significantly decreased, resulting in improved rat memory and cognitive impairments." (PMID 36365114, 2022). "The SCOP-induced cognitive deficit models in an in vivo study have been reported to reduce antioxidant enzyme activity and exhibit cholinergic dysfunction, like increased AChE and decreased ACh as in AD patients." (PMID 36552705, 2022). "Xanthone derivatives of G. mangostana have been reported for neuroprotection against lead-induced acetylcholinesterase (AChE) dysfunction and cognitive impairment in mice." (PMID 36590574, 2022). "As we expected, this study found that THPH administration altered gut microbiota diversity in cognitive impairment mice, including increasing the abundance of Actinobacterota, which produced metabolites with anti-AchE activity." (PMID 34945680, 2021). "On this background, the use of drugs inhibiting the enzyme acetylcholinesterase (AChE) remains an eternal evergreen in the symptomatic treatment of mild to moderate cognitive impairments." (PMID 33916760, 2021). "As BuChE has brought much attention compensating for the action of AChE in cognitive impairment, further studies will establish the detailed influence of stilbenoids on BuChE for a beneficial feature in AD treatment." (PMID 34073796, 2021).
Cognitive impairment (continued). "Current AD research is focused on the activation of cholinergic neurotransmitters by treating memory and cognitive impairment, and AChE, an enzyme that degrades ACh." (PMID 34445062, 2021). "The translational role of cholinergic signals associated with TBI has centered on mechanistic and clinical attempts to leverage AChE inhibition to curtail cognitive deficits and facilitate recovery but without significant success." (PMID 34489621, 2021). "In a rat model of cognitive impairment induced by scopolamine, canagliflozin, similarly to galantamine, decreased AChE activity, increased acetylcholine M1 receptor (M1 mAChR) and monoamines levels." (PMID 34885795, 2021). "Administration of ruthenium red (a RyRs antagonist) and montelukast (a CysLT1Rs antagonist) considerably attenuates CCH-induced cholinergic dysfunction by suppressing AChE activity, reducing the cognitive impairment and brain damage." (PMID 33532143, 2021). "We further clarified THPH’spossible mechanism of improving cognitive impairment and memory by studying the expression of AchE and ChAT genes in the brain." (PMID 34945680, 2021). "Some Gen derivatives also show a good inhibitory effect on AChE, thus improving cognitive disorder and dysmnesia in mice." (PMID 33704934, 2021). "By performing studies on mice models in HD (R6/1), it was evidenced that AChE activity was reduced and consequently they developed cognitive deficits in the middle stage of the disease." (PMID 34502198, 2021). "The presence of significantly elevated AChE activity indicates cholinergic damage in the hippocampus, which triggers cognitive deficits, in patients with VaD." (PMID 33532143, 2021). "For example, in a retrospective analysis patients with mild cognitive impairment, rivastigmine, which inhibits both AChE and butyrylcholinesterase (BChE, EC 3.1.1.8), reduces whole brain atrophy, hippocampal atrophy, and white matter loss." (PMID 32414155, 2020). "The cholinergic deficit in the cerebral cortex and basal forebrain results in the cognitive impairment of patients with AD, and AChE hydrolyzes acetylcholine into choline and acetate, which then reduces acetylcholine." (PMID 32711521, 2020). "Cognitive impairment of AD is correlated with a synaptic impairment in the cholinergic system, because of an insufficiency of ACh due to an increased content of AChE in the brain." (PMID 32392535, 2020). "Cognitive impairments in neurodegenerative diseases have been related to reductions in ACh and increased levels of AChE in the hippocampus." (PMID 32392535, 2020). "The mechanism by which severe hypoxia induced cognitive impairment was accompanied by a decrease in Acetylcholine (Ach) level and increase in Acetylcholinesterase (AChE) in the cortex." (PMID 32759658, 2020). "Dieckol was previously reported to improve cognitive impairment in ethanol-fed mice, partly due to increased level of acetylcholine and inhibited AChE activity in the brain." (PMID 31752064, 2020). "For AD therapy, the administration of acetylcholinesterase (AChE) inhibitors partially recovers cognitive deficits." (PMID 32486466, 2020). "AChE inhibitor therapy would best start at the earliest appearance of subtle cognitive impairment, a point at which signs of neurodegeneration are the earliest and most common biomarkers of AD and that often precede and predict the accumulation of amyloid." (PMID 32414155, 2020). "One pilot study showed that acetylcholinesterase (AChE) inhibitor promoted functional recovery in elderly patients with cognitive impairment who had suffered stroke." (PMID 31653081, 2019). "Conversely, co-administration of CA with D-gal/AlCl3 improved cognitive impairment, decreased AChE levels, attenuated the oxidative stress in hippocampus and cerebral cortex, and prevented ultrastructural alteration of neurons in the prefrontal cortex." (PMID 30935005, 2019).
Cognitive impairment (continued). "Previous in vitro and in vivo studies provided evidence that BIS-MEP inhibits AChE activity at nanomolar levels, inhibits AChE-induced Aβ aggregation and ameliorates scopolamine-induced cognitive deficits in mice." (PMID 30723404, 2019). "The protective effect of IRN against AlCl3-induced cognitive deficits is probably mediated, at least in part, through inhibiting the AChE activity and reducing the oxidative damage of brain tissue via inhibiting the activation of NF-κB signaling pathway." (PMID 29946349, 2018). "In conclusion, it is shown here that A10E, a new AChE inhibitor, prevented surgery-induced cognitive impairments in aged mice." (PMID 30483056, 2018). "In fact, AChE inhibitors were approved for cognitive disorders and are the most extensive in all anti-dementia drugs." (PMID 29370115, 2018). "Guarana powder prevented memory impairment and the decrease in acetylcholinesterase (AChE) activity in the hippocampus of hyperlipidemic rats, implying a beneficial effect of guarana on cognitive disorders." (PMID 30116496, 2018). "In conclusion, our study demonstrated, for the first time, that chronic or acute administration of EVR protected against cognitive impairments and deleterious alterations in oxidative status and AChE activity in the hippocampus of the STZ-AD rats." (PMID 30564080, 2018). "The inhibition of AChE will hinder cognitive defects stimulated by the plantar electric shocks, which indicates that miR-132 regulates the process of cognitive impairment after stress." (PMID 29118714, 2017). "Recent studies have also elucidated the involvement of acetylcholinesterase (AChE) in AD cognitive deficits." (PMID 29115888, 2017). "Does fucoxanthin reverse scopolamine-induced cognitive impairments solely via the direct inhibition of AChE?" (PMID 27023569, 2016). "Donepezil, a reversible AChE inhibitor, was employed as a positive reference drug for the treatment of cognitive deficits." (PMID 27556046, 2016). "Several AChE inhibitors, tacrine, donepezil, galantamine, rivastigmine, and memantine, have proven to improve cognitive deficits." (PMID 27556046, 2016). "Aiming to provide more information related to cognitive impairment and Se intervention, oxidative stress, inflammatory cytokines, and AChE activity were assessed." (PMID 26090073, 2015). "Use of acetylcholinesterase (AChE) inhibitors represents a promising possibility for treatment of cognitive disorder in schizophrenia and other psychiatric disorders." (PMID 24711997, 2014). "Inhibition of acetylcholinesterase (AChE) is still considered as the main therapeutic strategy against Alzheimer's disease (AD) and cognitive deficits." (PMID 25401145, 2014). "Considering the role of AChE and BChE in suppressing neurotransmitter acetylcholine levels, numerous studies have demonstrated its potential as a therapeutic target for alleviating cognitive impairments in AD and SZ." (PMID 40002349, 2025). "Our research on MsA in N2a/APP695swe cells and scopolamine-induced cognitive impairment mouse models demonstrates that MsA significantly elevates ACh levels while effectively inhibiting AChE and BChE enzymes, highlighting its regulatory function in the cholinergic system." (PMID 41007261, 2025). "Similarly, administration of extracts from Vernonia amygdalina, Amygdalus spinosissima, and Bergenia ciliata demonstrated protective effects against SCO-induced cognitive impairment by significantly reducing both AChE and BChE activity in treated animals." (PMID 40002547, 2025). "EGCG decreases AChE activity and increases cholinergic communication, which could reduce cognitive deficits." (PMID 40561856, 2025). "Emerging evidence suggests dietary protein hydrolysates can modulate this system, as demonstrated by whey derivatives reducing cerebral AChE activity and inflammation in cognitive impairment models, and oyster peptides restoring ACh levels while attenuating glial inflammation in zebrafish." (PMID 40509464, 2025).